CD2AP (CD2 associated protein)
Diseases named in the same sentence as CD2AP in open-access papers (continued):
Sharing a sentence is not in itself a finding about the gene and the disease.
Adult onset (1 paper, 2024). Onset of disease manifestations in adulthood, defined here as at the age of 16 years or later. "The commonest genes affected in adult-onset FSGS (COL4A3–COL4A5,GLA ) have ocular abnormalities but not the other frequently affected genes (ACTN4, CD2AP, INF2, TRPC6)." (PMID 37578539, 2024).
brain tumors (1 paper, 2024). "About one month later, all xenografted mice developed brain tumors that were clearly detected by MRI but cells with CD2AP overexpression formed bigger tumors than control cells." (PMID 39353894, 2024).
Cerebral atrophy (1 paper, 2015). Atrophy (wasting, decrease in size of cells or tissue) affecting the cerebrum. "Expression of the top five differentially expressed genes found by GWAS - MS4A6A, CD2AP, INPP5D, MEF2C and CLU – all have good correlation with Braak stage and cerebral atrophy." (PMID 26202100, 2015).
colitis (1 paper, 2024). Inflammation of the colon. "We further tested the mRNA and protein levels of the characterized genes in the intestinal mucosa of DSS-induced colitis mice and UC patients, and the results showed that the mRNA and protein levels of SLC7A11, NDUFS1, LRPPRC, and CD2AP were dramatically downregulated in DSS-induced colitis mice." (PMID 38977802, 2024).
glioma (1 paper, 2024). A benign or malignant brain and spinal cord tumor that arises from glial cells (astrocytes, oligodendrocytes, ependymal cells). "Furthermore, we found that high CD2AP expression was associated with poor survival rate of glioma patients." (PMID 39353894, 2024). "Here by studying public datasets, we found that CD2AP expression was significantly elevated in GBM and that glioma patients with increased CD2AP expression had a worse prognosis." (PMID 39353894, 2024). "Moreover, CD2AP expression was negatively correlated with the overall survival of glioma patients in both the GEPIA and the CGGA datasets." (PMID 39353894, 2024). "To further verify the involvement of CD2AP in GBM, we compared CD2AP levels between HEB cells and various glioma cell lines (SHG44, U87MG, and U251) and found that CD2AP levels were higher in glioma cells than in HEB cells." (PMID 39353894, 2024). "We found that CD2AP expression was significantly elevated in GBM samples compared to non-tumor tissues and low-grade glioma samples." (PMID 39353894, 2024). "Through analysis of the transcriptome expression profiles of public databases and study on available clinical samples and GBM cell lines, we found that CD2AP expression was significantly upregulated in GBM samples compared to non-tumor and low-grade glioma samples." (PMID 39353894, 2024).
ischemia (1 paper, 2019). A hypoperfusion of the BLOOD through an organ or tissue caused by a PATHOLOGIC CONSTRICTION or obstruction of its BLOOD VESSELS, or an absence of BLOOD CIRCULATION. "Q-PCR and Western Blot further showed that the mRNA and protein expressions of Synaptopodin, Nephrin, and CD2AP decreased by ischemia in a time-dependent manner, while the expression of TRPC6 mRNA and protein increased in a time-dependent manner." (PMID 30922260, 2019).
kidney tumors (1 paper, 2024). "For example, CD2AP was found to display a specific expression pattern in human urogenital organs but distinct expression patterns in several types of kidney tumors." (PMID 39353894, 2024). "The expression pattern of CD2AP was also altered in several types of kidney tumors, implicating its involvement in kidney tumors." (PMID 39353894, 2024).
leukemia (1 paper, 2021). A malignant (clonal) hematologic disorder, involving hematopoietic stem cells and characterized by the presence of primitive or atypical myeloid or lymphoid cells in the bone marrow and the blood. "It should be noted that the stable interaction of CD2AP with STS1 has also been confirmed recently by the BioID approach in leukemia cells." (PMID 33397984, 2021).
memory impairment (1 paper, 2025). "Finally, beyond the capillary blood cell data that link cerebrovascular function to cognition, all the other morphological, functional and pathological changes resulting from the loss of CD2AP in brain endothelial cells are likely contributing to their memory impairment." (PMID 40462155, 2025). "These mice also exhibit reduced vessel density in the hippocampus and higher markers of microglia and macrophage activation at 15 months of age suggesting that long-term loss of CD2AP might damage brain vessels, increase brain inflammation and contribute to memory impairment." (PMID 40462155, 2025).
minimal change disease (1 paper, 2019). "The authors demonstrated this with 3 mouse models (Cd2ap-KO, Lamb2-KO, and Adriamycin) and 3 examples of human nephrotic disease (minimal change disease, FSGS, and diabetic nephropathy)." (PMID 30899761, 2019). "Nephrotic diseases studied included minimal change disease in human biopsies, Heymann nephritis in a rat model, Lamb-2, and Cd2ap mouse knockout models and an Adriamycin injury mouse model." (PMID 30899761, 2019).
neuroblastoma (1 paper, 2015). Neuroblastoma (NB) is the most common solid, extracranial childhood tumor. "In this study, we decreased CD2AP levels in N2a neuroblastoma cultures and PS1APP mice and analyzed Aβ levels and plaque burden." (PMID 25887956, 2015).
Obesity (1 paper, 2021). Accumulation of substantial excess body fat. "The mRNA expression of nephrin, synaptopodin, and CD2AP in urine sediment was not significantly different between the groups, irrespective of the degree of obesity." (PMID 34575240, 2021).
osteoarthritis (1 paper, 2014). A noninflammatory degenerative joint disease occurring chiefly in older persons, characterized by degeneration of the articular cartilage, hypertrophy of bone at the margins and changes in the synovial membrane. "HLA-DRB1 and CD2AP gene were identified to be among the susceptibility genes of KBD, thus supporting the role of the autoimmune response in KBD and the possibility of shared etiology between osteoarthritis, rheumatoid arthritis, and KBD." (PMID 24776925, 2014).
osteosarcoma (1 paper, 2018). A usually aggressive malignant bone-forming mesenchymal neoplasm, predominantly affecting adolescents and young adults. "Knocking out PAWS1 from U2OS osteosarcoma cells causes actin cytoskeletal and cell migration defects similar to those caused by the loss of CD2AP, suggesting that the association between PAWS1 and CD2AP plays an important role in regulating cytoskeletal dynamics and cell migration." (PMID 29175910, 2018). "By knocking out PAWS1 from U2OS osteosarcoma cells, we show here that PAWS1 plays a role in actin organization, morphology, spreading and migration in U2OS cells, and that it is likely to exert these effects through its interaction with CD2AP." (PMID 29175910, 2018).
Sepsis (1 paper, 2022). Sepsis is defined as life-threatening organ dysfunction caused by a dysregulated host response to infection. "In conclusion, this work showed circVMA21 improved LI in sepsis rats by targeting miR-497-5p/CD2AP axis, suggesting that circVMA21 may be a novel therapeutic target for sepsis-induced LI." (PMID 35172672, 2022).
steatosis (1 paper, 2022). Increased lipid within the cytoplasm of cells. "One study has shown that hepatitis C virus-infected cells have higher levels of CD2AP, which promotes hepatitis C virus transmission and steatosis by disrupting insulin signaling." (PMID 36359915, 2022).
type I diabetes (1 paper, 2019). "Pathway analysis identified endocytosis, phagosome, autoimmune, type I diabetes as enriched pathways in downregulated genes of Cd2ap+/− mice, while there was no pathway enrichment in upregulated genes of Cd2ap+/− mice." (PMID 31878951, 2019).
uterine corpus endometrial carcinoma (1 paper, 2023). A endometrial carcinoma (disease) that involves the body of uterus. "CD2AP had the lowest methylation level in uterine corpus endometrial carcinoma (UCEC), and IQGAP1 had the highest methylation level in UCEC." (PMID 38235128, 2023).
tumor (20 papers, 2011 to 2025). "The expression level of CD2AP was proven to be associated with TMBs, immune cell infiltrations, and tumour T stages in subsequent analysis." (PMID 41425578, 2025). "CD2-associated protein was found to be less abundant in the deep part of the tumor, consistent with a study demonstrating the increased FN expression in silenced cells for CD2-associated protein, and the capacity of this protein to regulate migration and EMT-related pathways in CRC cells." (PMID 39195201, 2024). "In addition, abnormalities in CD2AP expression and function may be associated with tumour cell invasiveness and drug resistance." (PMID 41425578, 2025). "The Tyrosine Kinase Substrate with four SH3 domains (TKS4) and the CD2-associated protein (CD2AP) have previously been linked to dynamic actin assembly related processes and cancer cell migration, although their co-instructive role during tumor formation remained unknown." (PMID 37894817, 2023). "Specifically, an elevation in the expression levels of PRN1, OXSM, SLC3A2, and CD2AP were observed in tumor tissues, while the expression levels of DSTN, FLNA, TLN1, IQGAP1, MYL6, NCKAP1, and NDUFS1 declined in tumor tissues." (PMID 39995998, 2025). "Subsequently, we assessed CD2AP expression in paired tumour and adjacent normal tissues from five LUAD patients using Western Blot (WB)." (PMID 41425578, 2025). "Studies have shown that CD2AP is involved in regulating cytoskeletal and endosomal-lysosomal pathways, which affects the proliferation, migration, and invasive ability of tumour cells." (PMID 41425578, 2025). "The results demonstrated that CD2AP expression was significantly upregulated in monocytes, endothelial cells, and NK cells within tumour tissues compared to their counterparts in normal tissues." (PMID 41425578, 2025). "Our study found that CD2AP mRNA was upregulated in tumour tissues, and its higher expression predicted a poor prognosis for LUAD patients, suggesting that it functions as a cancer-promoting gene." (PMID 41425578, 2025). "Seven studies containing 827 LUAD samples and 246 normal tissues were enrolled, although with significant heterogeneity; CD2AP was identified as being enriched in tumour samples in most studies." (PMID 41425578, 2025). "The results revealed that CD2AP was not only expressed in tumour cells but was also notably enriched in mononuclear macrophages." (PMID 41425578, 2025). "To further explore the role of CD2AP in tumour cells and monocytes, we stratified these two cell types into CD2AP+ and CD2AP- subgroups using expression thresholds of 0.2094 and 0.1546, respectively." (PMID 41425578, 2025). "The results confirmed that CD2AP protein levels were significantly elevated in tumour tissues, with the quantitative analysis shown in the corresponding histogram (P < 0.05)." (PMID 41425578, 2025). "The functional role of CD2AP within monocytes/macrophages and how it contributes to tumour progression remain to be fully elucidated and represent an important direction for future research." (PMID 41425578, 2025). "We identified CD2AP as a key molecular, as its mRNA and protein levels were elevated in tumour tissues; meanwhile, higher expression of CD2AP predicted poorer clinical outcomes across multiple databases." (PMID 41425578, 2025). "We then subjected CD2AP to rigorous multi-omics and experimental validation to delineate its oncogenic functions, impact on the tumour immune microenvironment, and therapeutic potential." (PMID 41425578, 2025). "scRNA-seq confirmed CD2AP enrichment in monocytes and revealed enhanced communication between CD2AP+ tumour cells and monocytes." (PMID 41425578, 2025). "Prior staging analysis suggested CD2AP likely functions as an oncogene and is highly expressed in tumour cells." (PMID 41425578, 2025). "Tumour tissue from a LUAD patient (Patient ID: 2438) exhibited a vigorous staining intensity of CD2AP, confirming that the CD2AP protein was predominantly cytoplasmic and membrane-expressed." (PMID 41425578, 2025).
tumor (continued). "Through the integration of multi-omics data and functional experiments, we demonstrated that CD2AP promotes tumour cell proliferation and migration." (PMID 41425578, 2025). "It is plausible that in CD2AP-high tumours, the oncogenic activity is partly dependent on a synergistic interplay between EGFR signalling and CD2AP-mediated scaffolding and endocytosis." (PMID 41425578, 2025). "We conducted a comprehensive bioinformatic analysis to investigate the mRNA and protein expression levels of Tks4 and its associated partner molecules (CD2AP, GRB2, WASL, SRC, CTTN, and CAPZA1) across different tumor types." (PMID 39234565, 2024). "FLNB, SLC7A11, and CD2AP were lowly expressed in almost all major cell types, but significant expression difference was also found in fibroblasts between tumor and normal tissue." (PMID 38694875, 2024). "In the deep tumor region, a similar correlation was observed for PLD3, alphaB-crystallin, CCN family member 2 or connective tissue growth factor (CTGF), and CD2-associated protein, while OGDH-E1 showed an opposite trend." (PMID 39195201, 2024). "Consistently, the confusion matrix statistics showed that the normal and tumor samples can be reliably separated using gene expression data for CD2AP, GRB2, WASL, SRC, CTTN, CAPZA1, and Tks4 with 97% sensitivity and 80% specificity." (PMID 39234565, 2024). "A cytoskeletal protein, CD2AP, is specifically detected in MDSCs in response to 4T1 metastatic tumor burden." (PMID 21853032, 2011). "The single-cell analysis revealed that CD2AP was primarily enriched in mononuclear macrophages, highlighting its critical role in mediating intercellular communication between tumour cells and monocyte subsets, thereby illuminating a previously unrecognised mechanism of tumour-stroma crosstalk." (PMID 41425578, 2025). "Our docking prediction raises the hypothesis that dasatinib’s efficacy might be augmented in CD2AP-high tumours by concurrently inhibiting SRC kinases and disrupting CD2AP-dependent invasive structures." (PMID 41425578, 2025). "Moreover, CD2AP overexpression promoted the malignancy of GBM cells and their tumorigenicity in the intracranial xenograft tumor model, whereas CD2AP knockdown had the opposite effects." (PMID 39353894, 2024). "In addition, siRNA/shRNA-mediated CD2AP silencing could also potentially inhibit tumor metastasis, building on the existing delivery platforms from other oncogene-targeting trials." (PMID 40362690, 2025). "Therefore, the role of CD2AP in various types of tumours is inconsistent." (PMID 41425578, 2025). "We further explored the correlations between CD2AP mRNA levels and clinical features (age, gender, tumour stage, and TNM stages), and the results showed that, compared to the T1 stage, CD2AP levels were significantly higher in the advanced stages (T2-T4)." (PMID 41425578, 2025). "Results showed that ACTB, DSTN, FLNA, IQGAP1, MYL6, and TLN1 were overexpressed in normal tissues, while CD2AP and INF2 were overexpressed in tumor tissues." (PMID 37325625, 2023). "The tumor cells of BPDCN and PPDM share the common characteristic phenotype of pDCs: lin−, CD4+, CD68+, CLA+, CD123+, BDCA2+, Bcl11A+ and CD2AP+." (PMID 25779340, 2015). "Based on the strong correlation and the finding that monocytes themselves express high levels of CD2AP in the TME, we hypothesise that the CD2AP-high ecosystem–comprising both tumour cells and immune cell–may foster a pro-tumoural environment." (PMID 41425578, 2025). "Our histological and cytological experiments demonstrated that both the protein and mRNA expression levels of CD2AP were significantly elevated in tumour tissues compared to adjacent non-cancerous tissues." (PMID 41425578, 2025). "CD2-associated protein and CTGF, despite exhibiting opposite variations in the deep part of the tumor, showed a similar negative correlation with the budding index, with higher abundances in patients with lower budding." (PMID 39195201, 2024).
tumor (continued). "Finally, we acquired GBM tissues and brain tissues from non-tumor patients and confirmed that CD2AP levels were significantly increased in GBM (grades IV) tissues than in non-tumor tissues and low-grade tumor tissues (I, II and III)." (PMID 39353894, 2024). "Finally, as the interaction between CD2AP and TKS4 might play a role in tumor development, targeting this protein–protein interaction might be a novel approach for inhibiting cancer metastasis." (PMID 37894817, 2023). "In addition, CBLC may not always lead to the destabilization of RET, but cause exactly the opposite in the absence of an interacting protein, CD2AP, thereby potentially also stimulating tumor formation." (PMID 38045004, 2023).
cancer (18 papers, 2013 to 2025). A tumor composed of atypical neoplastic, often pleomorphic cells that invade other tissues. "The hypermethylated genes SLC7A11 and CD2AP were primarily associated with better prognosis in cancer, whereas the hypomethylated gene MYL6 was predominantly associated with poor prognosis in PCPG." (PMID 38862242, 2024). "Several studies have suggested that CD2AP was associated with but exhibited different functions in various malignant tumors." (PMID 39353894, 2024). "As CD2AP was identified as a hub gene in our study, we first conducted a pan-cancer analysis to compare the mRNA levels between cancers and the corresponding normal tissues." (PMID 41425578, 2025). "Cell communication analysis indicated strong interactions between CD2AP+ cancer cells and monocytes, predominantly mediated by the APP-CD74, MIF-CD74_CD44, and SCGB3A2-MARCO pathways." (PMID 41425578, 2025). "Consistent with our results, we further demonstrated that CD2AP-expressing cancer cells mediate intercellular communication with monocytes primarily via the APP-CD74 pathway." (PMID 41425578, 2025). "Recently, CD2-associated protein (CD2AP) and tyrosine kinase substrate with four SH3 domains (TKS4) have emerged as potential cancer formation-regulating factors." (PMID 37894817, 2023). "CD2AP was mainly expressed in the cytoplasm of the cancer cells, with some expression detected in the nucleus." (PMID 31989722, 2020). "More surprisingly, in vitro experiments showed that CD2AP was highly expressed in both HCC tissues and cells, and knockdown of CD2AP inhibited the capabilities of proliferation, migration, and invasion in Huh7 and HepG2 cells, which is consistent with the oncogenic role of CD2AP in other cancers." (PMID 40362690, 2025). "To explore the underlying mechanism by which CD2AP regulates GBM cell malignancy, we performed GSEA analysis using the CGGA and TCGA data and found that CD2AP was positively correlated with multiple molecular pathways of malignant tumors, including the NF-κB signaling." (PMID 39353894, 2024). "Moreover, several studies have suggested that CD2AP is involved in certain malignant tumors." (PMID 39353894, 2024). "Taken together, CD2AP could modulate both cancer cells and immune cells." (PMID 38694875, 2024). "Therefore, we hypothesized that the TKS4/CD2AP complex cooperatively regulates cytoskeletal rearrangements during cancer progression and participates in EMT process initiation." (PMID 37894817, 2023). "However, the functions of CD2AP in cancers remain largely unknown." (PMID 41425578, 2025). "On the other hand more research would be necessary to investigate the CD2AP and WASL co-regulated molecular events during cancer pathogenesis, which might be controlled by Tks4." (PMID 39234565, 2024).